MYD88 (MYD88 innate immune signal transduction adaptor)
Diseases named in the same sentence as MYD88 in open-access papers (continued):
Sharing a sentence is not in itself a finding about the gene and the disease.
cancer (continued). "MyD88 is also one of the markers of cancer cell stemness and is among the factors responsible for OC chemoresistance." (PMID 36231099, 2022). "Myd88 is a molecular complex involved in regulation of cardiovascular and cancer metabolism as well as in cancer cell survival and chemo resistance." (PMID 34178667, 2021). "In cancer cells, MyD88 constitutively inhibits MKP3 phosphatase activity on MEK1/2, which results in constitutive MEK1/2 activation." (PMID 33658617, 2021). "As shown in the Oncodrive plot, MYD88, CD79B, KHL6, and MUC4 were identified as cancer driver genes in the high-risk group whereas only PEG3 and ZNF337 were identified in the low-risk group." (PMID 34745101, 2021). "MyD88 is a molecular complex involved in regulation of the immune system, cardiovascular, and cancer metabolism." (PMID 33096896, 2020). "Together, these data demonstrate that periodontal pathogens contribute to a highly aggressive cancer phenotype via crosstalk between TLR/MyD88 and integrin/FAK signaling." (PMID 33002094, 2020). "It was previously reported that Ras pathway activation is maintained in the presence of MyD88 and linked to the induction of the DNA repair enzyme ERCC1, enabling efficient DNA repair mechanisms in cancer cells." (PMID 32422978, 2020). "The TLR4/myeloid differentiation factor 88 (MyD88) pathway has been recognized as oncogenic signaling in human cancers and is correlated with patients’ poor survival." (PMID 33195243, 2020). "TLR4 and its adaptor MyD88 have been reported as oncogenic signaling in several human cancers, including HCC." (PMID 33195243, 2020). "Based on the findings, it is recommended that a targeted delivery of the TLR3 ligand to the endosomal compartment, bypassing the MyD88 signaling and subsequently causing activation of the TRIF signaling, can trigger the apoptotic cascade in cancer cells." (PMID 33072559, 2020). "Myeloid differentiation primary response 88 (MyD88) is responsible for cell survival, DNA repair, and maintenance of stemness, thereby contributing to therapeutic resistance in cancer." (PMID 33066509, 2020). "Among them, the expression of AIM2/ASC/IL-18, MyD88, DAI, DHX36, and DDX60 were associated with cancer stages." (PMID 31949493, 2020). "In the present study, MyD88 expression was evaluated from normal mucosa to inflammation and carcinoma restricted to gastric cardia tissue." (PMID 32477927, 2020). "We observed that MyD88 expression gradually increased from normal tissue, gastric cardia inflammation, and carcinoma." (PMID 32477927, 2020). "Considering that MYD88 is upstream of NF-kappa B which itself regulates the cell cycle and other cancer related pathways, we selected it as a candidate for validation by inhibition." (PMID 31685921, 2019). "Studies have shown that MyD88 plays an important role in mediating the development of cancer and PTX resistance." (PMID 31259152, 2019). "The role of TLR stimulation (and similarly, IL-1β, which shares the MyD88 signalling pathway) in cancer progression is somewhat contentious and appears to depend on the specific TLR in question." (PMID 29415982, 2018). "Then, a second sequencing targeting MYD88 c.T778C was performed and compared to plasma samples from 25 age-matched control patients suffering from other types of cancer." (PMID 28636991, 2017). "Studies on the role of MyD88 cancer progression have been the subject of recent intense investigations." (PMID 28201999, 2017). "Modulators of the TLR/MyD88 pathway are currently under investigation in clinical trials for cancer treatment." (PMID 28662055, 2017). "Herein we provide evidence that the anti-cancer efficacy of topical ingenol mebutate treatment requires both MyD88 and IL-1." (PMID 27100888, 2016). "Characterization of EOC cells that express TLR4/MD-2 and MyD88 have helped to confirm the dynamic role of the immunosuppressive microenvironment in promoting cancer metastasis and recurrence." (PMID 27118139, 2016).
cancer (continued). "A total of 5 genes were annotated for both cancer and inflammation: Fcgr2b, Egfr, Tnfaip3, Fas and Myd88." (PMID 27566565, 2016). "Previous studies have shown that MyD88-activated R182 cells can produce pro-inflammatory and pro-tumorigenic cytokines, which can confer resistance to anti-cancer drugs." (PMID 27708225, 2016). "The data so far supports the view that IL-1 promotes the anti-cancer efficacy of ingenol mebutate by promoting neutrophil anti-cancer activity, with MyD88 required for IL-1 receptor signal transduction." (PMID 27100888, 2016). "This supports the involvement of innate immune signalling in cognitive dysfunction, and identifies MyD88 signalling pathways as a potential focus for predicting and reducing the burden of cognitive dysfunction in cancer pain patients." (PMID 26332828, 2015). "This study aims to provide further evidence that MyD88 positive cancer cells are clinically significant, stem-like and reproducibly detectable for the purposes of prognostic stratification." (PMID 24977712, 2014). "Interaction of MYD88 with Beclin1 reduces Beclin1 binding to Bcl-2, which leads to autophagy induction in cancer cells." (PMID 24527027, 2014). "The signaling pathway of TLRs in cancer tissue is different from that in normal cells; and is MyD88-independent." (PMID 25547486, 2014). "In parallel, expression of TLR4 and MyD88 mRNA and regulatory microRNAs (miR-21 and miR-146a) was assessed, as well as in a series of chemosensitive and resistant cancer cells lines." (PMID 24977712, 2014). "The expression of MyD88 in malignant tumors was considerably greater (18/24) than that in normal ovarian tissue (1/8) or borderline tumors (1/12)." (PMID 24527095, 2014). "MyD88 positive cancers analysed in this study recurred 18 months earlier than MyD88 negative cancers, with a similar reduction in overall survival of 19 months (p<0.05)." (PMID 24977712, 2014). "Increased MyD88 mRNA expression was observed in all chemoresistant cancer cell lines; these changes were small but statistically significant." (PMID 24977712, 2014). "TLRs’ signaling pathway in cancer tissue is different from that in normal cells and is MyD88-independent." (PMID 25547486, 2014). "Adjuvant studies for cancer vaccine treatments have recently focused on TLR4 agonists because these receptors mediate signals from the innate immune system via MyD88- and TRIF-dependent pathways, and these appear to be important immunopotentiators." (PMID 25102137, 2014). "The present study revealed that the proliferation and survival of the cancer cells is regulated by a specific defense mechanism in TLR4/MyD88 signaling." (PMID 24527095, 2014). "It has been recently shown that TLR9 stimulation with agonistic CpG sequences stimulates invasion in various cancer cells via MYD88-independent and TRAF6 partially dependent pathways." (PMID 24459426, 2013). "In EOC, a total of 64 of 83 (77.11 %) cancers showed MyD88 expression, but a variably strong or weak signal (4+: 9, 3+: 19, 2+: 18, 1+: 18, 0: 19)." (PMID 22533866, 2012). "As MyD88 is clearly involved in infectious disease, cancer, and autoimmune diseases, it is obviously an attractive target for intervention in these diseases." (PMID 20981241, 2010). "Similarly, CIBERSORT estimates of immune cell infiltration showed that patients with high MyD88 expression had more cancer-suppressing immune cells, such as M1 macrophages, and fewer cancer-promoting immune cells, such as M2 macrophages." (PMID 39744584, 2025). "It is pivotal for the development of drugs targeting MyD88-dependent inflammation and cancer." (PMID 40771916, 2025). "The TOLLIPTLR4/MyD88/NF-κB regulatory pathway has been mainly reported in inflammatory diseases, and it is still unclear whether it plays a regulatory role in cancer." (PMID 39735680, 2025).
cancer (continued). "Moreover, the effect of AMK on signaling pathways such as Wnt/β-catenin, TLR4/MyD88, and mitochondrial pathways suppress cancer cell proliferation, increase cancer cell apoptosis, and improve responses to chemotherapy agents." (PMID 40144663, 2025). "The most typical type of cancer induced by MyD88 is DLBCL, particularly WM." (PMID 38785969, 2024). "Based on the specificity and importance of MyD88 in regulating immunity and cancer progression, related inhibitors may provide new insights into cancer treatments." (PMID 38785969, 2024). "Additionally, based on optimal activation of Ras/ERK, MyD88 promotes DNA damage repair and self-protection in cancer cells." (PMID 38785969, 2024). "Current strategies targeting MyD88 including inhibition of signaling pathways and protein multimerization, have made substantial progress, especially in inflammatory diseases and chronic inflammation-induced cancers." (PMID 38785969, 2024). "Meanwhile, the combination of MyD88-targeted therapies and immunotherapy may bring more hope for cancer cure in the near future." (PMID 38785969, 2024). "However, research often focuses on the specific deletion of MyD88, with insufficient attention to the loss of different TLR subtypes, impeding our understanding of the diverse roles of TLRs in cancer." (PMID 38523155, 2024). "In addition, our study discusses the potential advantages and prospects of MyD88-targeted drugs in cancer therapy and proposes potential strategies for drug development and disease treatment." (PMID 38785969, 2024). "Given the positive correlation between MyD88 and M2-macrophages, inhibition of MyD88 may be a promising anti-cancer therapeutic strategy." (PMID 38785969, 2024). "Present data suggests that both TLR4 and MyD88 have been involved in the progression of multiple cancers, but they also demonstrate a protective role when stimulated or inhibited depending on the cancer type or stage; thus, two TLR4 ligands have already been approved for cancer treatment." (PMID 39000291, 2024). "In addition to being anti-inflammatory, other MyD88 inhibitors have shown unexpected anti-cancer effects." (PMID 38785969, 2024). "For instance, TLR4-mediated sensing of vesicular stomatitis virus (VSV) by cancer cells leads to the activation of MyD88 signaling, which results in the induction of type-1 interferon signaling, tumor and lymph node infiltration of T cells and dendritic cells, and overall anticancer immunity." (PMID 38731910, 2024). "The importance of MyD88 in the development of various cancers has been emphasized previously." (PMID 39000291, 2024). "Additionally, previous research has shown that MYD88 expression is increased in cancer tissues and correlated with paclitaxel resistance in other cancers such as breast, ovarian, and lung." (PMID 39065761, 2024). "Additionally, oncolytic adenoviruses have been demonstrated to activate TLR2 on cancer cells, leading to MyD88-dependent interferon responses and subsequent immune activation." (PMID 38731910, 2024). "MyD88 serves as a significant inflammatory signaling pathway in the context of illness and cancer." (PMID 38334644, 2024). "As we know TLR4/MyD88 signaling plays vigorous roles in several cancers." (PMID 37822929, 2023). "Therefore, identifying aberrant MyD88 expression is employed to predict prognosis of various human cancers (e.g., lymphoid, liver, hepatic, gastric and colorectal cancers." (PMID 37822929, 2023). "To determine if MyD88 transduces LPS/TLR4 signaling to induce cancer apoptosis in the presence of an IAP antagonist, we investigated the effect of a small molecular compound, called 4210, which blocks MyD88 dimerization, on the apoptosis of MDA-MB-231 cells induced by LPS+SM-164." (PMID 36119107, 2022). "MyD88 is involved in the development of various cancers by acting downstream of TLRs." (PMID 35127830, 2022).
cancer (continued). "Indeed, the regulation of MDSC immunosuppressive functions plays a critical role in successful immunotherapy against cancer; moreover, Myd88 signaling is involved in the regulation of the immunosuppressive functions of MDSCs." (PMID 35089465, 2022). "Inhibition of NF-κB after MyD88 activation induces apoptosis in cancer cells." (PMID 34844644, 2021). "As a result of MyD88 engagement by TLRs, cancer cells undergo apoptosis." (PMID 34671606, 2021). "Based on previous findings, we could deduce that MYD88 and TLRs/IL-1R pathway might both participate in the cancer cell progression and the polarization of M2 macrophage." (PMID 33898320, 2021). "One potential mechanism underlying chemoresistance to 5-FU and oxaliplatin is the ability of Fn to target innate immune signaling pathways such as Toll-like receptor 4 (TLR4) and activating Myeloid differentiation primary response 88 (MyD88) in cancer cells to activate autophagy pathway." (PMID 34642332, 2021). "MyD88 signaling represents a survival signal for this type of cancer." (PMID 35069570, 2021). "The importance of TLR-MYD88-NFκB signaling is supported by muscle-wasting models of cancer cachexia and by the demonstration that MyD88 mRNA is inversely correlated to a quadricep’s cross-sectional area and muscle strength during recovery from hip fracture surgery in older adults." (PMID 33926035, 2021). "Undoubtedly, with the availability of powerful sequencing techniques the analysis of alternative splice isoforms of MyD88 pathway members for discovering novel non-mutational cancer drivers is both possible and warranted." (PMID 34163463, 2021). "IL-33/ST2 signaling activates myeloid differentiation primary response 88 (MyD88)/interleukin-1 receptor (IL-1R) associated kinase (IRAK)/TNF receptor-associated factor 6 (TRAF6) pathway in the majority of cell types, including cancer cells, stromal cells, and immune cells." (PMID 34209038, 2021). "In principle, inhibition of MyD88-mediated signaling by caspase-1 cleavage might be able to inhibit cancer growth." (PMID 35069570, 2021). "The lack of significance of MyD88 as a prognostic factor in GCC might be due to the complex role of MyD88 in cancer tissue, and we need further studies to provide evidences." (PMID 32477927, 2020). "The effects of MyD88 in the development and progression of cancers are controversial." (PMID 32477927, 2020). "TLR9 likely promotes stemness in cancer cells via MYD88 and STAT3." (PMID 32843056, 2020). "In normal part of cancer samples, the expression of genes that negatively regulate the MyD88-independent TLR signaling pathway and genes that positively regulate prostaglandin E synthesis were enhanced in CD14+CD11c+CD163low cells compared to CD14−CD11c+ cells." (PMID 32076066, 2020). "MyD88 is also targetable and such treatments may potentially eradicate paclitaxel resistant cancer stem cells (CSCs) by inducing differentiation." (PMID 33370338, 2020). "In colon cancer models, MyD88 showed contradictory roles even in the same cancer." (PMID 32477927, 2020). "MyD88 also positively correlated with NF-κB p105/p50 expression (p = 0.012) in cancer tissue." (PMID 32477927, 2020). "MyD88 complex (called myddosome) is another protein regulator of death-like signals in human cells; it is a putative marker of the incidence and prognosis of cardiovascular diseases and cancer." (PMID 33096896, 2020). "Additionally, these immune cells also play a role in cancer cell invasion, angiogenesis and metastasis by recruiting myeloid differentiation primary response gene 88 (MyD88) or TIR-domain-containing adapter-inducing interferon-β (TRIF) adaptor molecules." (PMID 30567565, 2018).
cancer (continued). "In addition to these signaling pathways, the classical TLR4/MyD88 signaling pathway is also responsible for cancer progression." (PMID 29338742, 2018). "Our NGS-based approach identified exploitable genomic alterations such as gain-of-function MYD88 oncogene mutations and loss of the tumor suppressor CDKN2A, and thus illuminates new routes to biologically targeted therapies for VRL, a cancer with a dismal prognosis." (PMID 28002793, 2017). "This evidence suggests that aberrant elevation of MyD88 expression may have a critical role in maintaining the malignant features in this type of cancer." (PMID 28662055, 2017). "Low MyD88 expression in these aggressive cancer cells argues that TLR/IL-1 signaling may promote anti-cancer responses at this stage of disease and again dysregulation of miR-21 in the tumor acts to promote pathogenesis of disease progression." (PMID 25688245, 2015). "Further this may prompt the investigation of interventions targeting the MYD88 pathway to ameliorate cognitive dysfunction in cancer patients, similar to those being trialled for post-operative cognitive dysfunction." (PMID 26332828, 2015). "Elevated MyD88 expression has been found in parenchymal cells in various types of cancer." (PMID 26223974, 2015). "Similarly, MyD88 has previously been closely related to the occurrence, development, drug resistance and metastasis of cancer." (PMID 25691060, 2015). "It is probable that the protective effect of the MYD88 rs6853 variant is due to reduced innate immune activation in response to DAMPS associated with cancer and/or chemotherapy tissue damage, rather than to fentanyl." (PMID 26332828, 2015). "The results from IFN-α and MyD88 in cancer tissues suggested that the TLR8 signaling pathway may be different in cancer tissues from the antiviral responses in which TLR8 induces antiviral responses by MyD88-dependent-producing IFN-α." (PMID 25547486, 2014). "Another important function of both the exo-Hsp70 and of the endo-Hsp70 released from cancer cells may be the stimulation of MyD88/IRAK4-dependent pathway." (PMID 24797019, 2014). "Such MyD88 competent cancer cells are theoretically able to exploit current chemotherapeutic strategies, by not only resisting their cytotoxic effects but also by using paclitaxel-ligation to facilitate their growth and that of the surrounding stroma via enhanced NF-κB production." (PMID 24977712, 2014). "We hypothesise that MyD88+ cancer cells represent a subpopulation of cells in EOC that confer more aggressive biological behaviour and chemoresistance." (PMID 24977712, 2014). "However, the expression of MyD88 in malignant tumors was considerably greater (18/24) than that in normal ovarian tissue (1/8) or in borderline tumors (1/12)." (PMID 24527095, 2014). "Eleven cancers displayed high expression, and seven cancers showed low expression of MyD88." (PMID 25547486, 2014). "The results of this analysis are in exact concordance with recent reports indicating reductions in disease-free intervals and patient survival with MyD88 positive cancers, ranging from 11–35 month reductions in progression-free survival and 26–36 month reductions in overall survival." (PMID 24977712, 2014). "In addition, 40 (48 %) cancers showed a high-level combined expression of TLR4/MyD88 (6+: 17, 7+: 15, 8+: 8)." (PMID 22533866, 2012). "In CRC, a total of 93 of 108 (86%) cancers showed MyD88 expression." (PMID 20145615, 2010). "Our findings suggest that TLR4/MyD88 signalling contributes to CRC tumourigenesis not just in colitis-associated cancer but also in sporadic CRC." (PMID 20145615, 2010). "In addition, 25 (23%) cancers showed a high-level combined expression of TLR4/MyD88 (5+: 12, 6+: 5, 7+: 7, and 8+: 1)." (PMID 20145615, 2010).